Y_RNA (Y RNA )
Gene: Miscellaneous RNA gene on chromosome 18 (8,720,034 to 8,720,132, reverse strand). Ensembl gene ENSG00000252319.
Homologues: Orthologues: chimpanzee Y_RNA (98% identical), guinea pig Y_RNA (76% identical). Paralogues in human: RNY4P19 (83% identical), RNY4 (82% identical), RNY4P14 (81% identical), RNY4P36 (81% identical), RNY4P6 (81% identical), RNY4P7 (81% identical), Y_RNA (81% identical), RNY4P17 (80% identical), RNY4P3 (80% identical), RNY4P37 (80% identical), Y_RNA (80% identical), Y_RNA (79% identical), and 89 more.